INS (insulin)
Diseases named in the same sentence as INS in open-access papers (continued):
Sharing a sentence is not in itself a finding about the gene and the disease.
Insulin resistance (continued). "Insulin resistance and impaired insulin signaling due to chronic hyperglycemia in the brain may induce hyperphosphorylation of tau protein and accumulation of amyloid-β protein, which are hallmarks of Alzheimer’s disease." (PMID 30597861, 2018). "Other studies only evaluated insulin resistance or fasting plasma insulin." (PMID 30518023, 2018). "Since incretin generally improves insulin sensitivity, these findings suggest that low H3K9ac levels may contribute to insulin resistance." (PMID 30558244, 2018). "In addition, the calculated insulin sensitivity index (RQUICKIBHB) implied that the increasing glucose supply curvilinearly increased insulin resistance in goats." (PMID 30405429, 2018). "It is unclear whether there are other lipokines that also exert an insulin-sensitizing effect, and how these lipokines may act and interplay in states of insulin resistance." (PMID 30274245, 2018). "The extra insulin compensates for insulin resistance and normalizes glucose level." (PMID 30307959, 2018). "The exact relationships between high fat diet, insulin resistance, and type 2 diabetes are pathological accumulation roles of fatty acids or fatty acid derivatives such as polyunsaturated fat in muscle or liver, that produced impairment of insulin sensitivity." (PMID 29755549, 2018). "The mechanisms are yet to be investigated, but insulin resistance with secondary hyperinsulinemia is the most frequently proposed hypothesis because insulin might have a mitogenic effect by binding to the insulin-like growth factor-I receptor." (PMID 30486265, 2018). "Also, the crucial importance of hyperinsulinemia and insulin resistance in favoring myocardial hypertrophy is well recognized in the context of growth-stimulating effect of insulin or expansion of blood volume." (PMID 29631555, 2018). "Thus, our study analyzed the specific role of p8 in glucose intolerance and insulin resistance by means of insulin or glucose tolerance tests, clamp trials and metabolic chamber analysis in SD and HFD-fed mice." (PMID 30040846, 2018). "The development of hyperinsulinemia and insulin resistance in murine cardiac hypertrophy is due to pressure overload boosts in myocardial insulin signalling to Akt (in excess), which adds to left ventricular reconstruction at an accelerated level and ultimately, a shift to heart failure." (PMID 29484207, 2018). "Indeed, GH downregulates the expression of key modulators of insulin signaling and suppresses key signaling pathways involved in stimulation of glucose uptake in muscle and fat, further resulting in insulin resistance." (PMID 30034367, 2018). "Type 2 diabetes is noninsulin dependent and occurs as a result of insulin resistance and deficiency in insulin secretion." (PMID 30538754, 2018). "However, measures of insulin resistance provide understanding of the mechanism of resistance beyond that provided by serum insulin alone and are likely better indicators of insulin and glucose homeostasis." (PMID 29587682, 2018). "In obese patients, the increased efflux of FFAs from adipose tissue to the liver may induce defects in the insulin signaling pathway and contribute to insulin resistance." (PMID 28643267, 2018). "The only strong association observed between miRNAs and C-peptide was that with miR-106b-3p, a miRNA known to induce mitochondrial dysfunction and insulin resistance in muscle cells, and with putative target genes significantly over-represented in the insulin signaling pathway." (PMID 29346396, 2018). "Similarly to humans, aged mice display insulin resistance, and maintain glucose tolerance through a combination of increased insulin levels, β-cell mass, and β-cell function." (PMID 30546031, 2018). "At first insulin resistance is accompanied by a compensatory increase in insulin secretion by the β–cells and this could last several years." (PMID 29373500, 2018).
Insulin resistance (continued). "We also observed male-specific adipose tissue pathways such as Wnt and insulin signaling, which agrees with the observations that insulin resistance is strongly correlated with NAFLD mainly in males and that males with NAFLD have higher glucose and lower adiponectin levels than females." (PMID 30343673, 2018). "Hyperuricemia induces increased insulin secretion to compensate for insulin resistance." (PMID 29568712, 2018). "However, neither of these two reports are compelling because the underlying pathology of insulin resistance between women with PCOS and controls matched for age, adiposity (BMI), and varying degrees of insulin sensitivity is likely different." (PMID 30377436, 2018). "Impairment of insulin vascular action may represent a mechanism linking insulin resistance and CVDs." (PMID 30416448, 2018). "Inflammation and insulin resistance are closely linked, and inflammatory cytokines such as tumor necrosis factor alpha (TNFα) may inhibit insulin signaling and promote insulin resistance." (PMID 29576769, 2018). "Based on these observations, we propose an idea that NYT lowers serum glucose levels elevated under diabetic conditions by improving insulin resistance via elevation of the lowered body (interstitial) fluid pH, which increases the binding affinity of insulin to its receptor." (PMID 30538991, 2018). "To determine whether sex steroids have a role in male-specific insulin resistance in Mito-Ob mice, we investigated the effect of gonadectomy on insulin sensitivity by insulin tolerance test (ITT)." (PMID 30157935, 2018). "Additionally, Tβ4 improves glucose intolerance and ameliorates insulin resistance in mice by acting as an insulin sensitizer through the increased phosphorylation of Akt signaling level." (PMID 30225249, 2018). "This correlation is important because it helps us clarify the role of omentin, since adiponectin is an adipocytokine whose increase in plasma levels is related to decreased insulin resistance, improved insulin sensitivity, and increased anti-inflammatory markers." (PMID 30666216, 2018). "Another meta-analysis investigating the metabolic effects of myoinositol supplementation compared to control found beneficial effects of myoinositol with lower insulin resistance and insulin levels, as well as higher SHBG levels and a trend for reductions of androgens." (PMID 29780358, 2018). "The analysis showed that this causal pathway and the measures of insulin resistance and insulin response were not supported by epidemiological data." (PMID 30307959, 2018). "A 25(OH)D status in the highest 25(OH)D quartile range (≥ 34.9 ng/mL; range 34.9–62.5) was associated with lower fat mass, better insulin sensitivity, better beta cell function, and a non-significant signal of a lower prevalence of insulin resistance." (PMID 30477276, 2018). "After that, we evaluated the association between fetuin-A and monocyte subsets with insulin resistance characterized by HOMA-IR in patients without insulin injection." (PMID 29582352, 2018). "CGRP is known to promote insulin resistance and obesity by decreasing insulin release from β-cells." (PMID 30108548, 2018). "In the presence of pre-existing maternal obesity or excessive gestational weight gain results, insulin secretion is insufficient to overcome insulin resistance and maintain glucose homeostasis, resulting in hyperglycemia and glucose intolerance that is characteristic of GDM." (PMID 30400566, 2018). "Moreover, the triglyceride to high-density lipoprotein cholesterol (TG/HDL-C) concentration ratio has been shown to be a reliable index of insulin resistance, similar to the fasting serum insulin." (PMID 29434676, 2018). "Together with the exacerbated insulin resistance, insulin secretion may also become inadequate to meet the increased demands in the late stage of pregnancy, leading to gestational diabetes mellitus (GDM)." (PMID 30037087, 2018).
Insulin resistance (continued). "Lastly, TZD might be taken into consideration in patients with severe insulin resistance requiring high doses of insulin." (PMID 29511288, 2018). "Likewise, inhibition of OGA with O-(2-acetamido-2-deoxy-D-glucopyranosylidene) amino-N-phenylcarbamate (PUGNAc) induces insulin resistance in 3T3-L1 and rat primary adipocytes by perturbing both insulin-signaling pathway and glucose absorption." (PMID 30356686, 2018). "Stimulated leptin levels also had significant interactions with insulin sensitivity (homeostasis model of insulin resistance, P = 0.01), triglycerides (P = 0.0078), fasting glucose (P = 0.027), systolic blood pressure (P = 0.037), and high-sensitivity C-reactive protein (P = 0.027)." (PMID 29434574, 2018). "Localized increases of suppressor of cytokine signaling 3 (SOCS3), known as an inhibitor of leptin and insulin signaling specifically in the hypothalamus, may lead to leptin and insulin resistance." (PMID 29498693, 2018). "Conversely, others have suggested that a compensatory increase in brain insulin levels may overcome systemic insulin resistance in R6/2 mice." (PMID 29895889, 2018). "Suppression of insulin-dependent glucose transport suggests that activation of RAS in podocytes may contribute to the development of insulin resistance." (PMID 30087656, 2018). "To determine whether HK L-137 affects insulin resistance in MetS rats, we performed insulin tolerance test (ITT)." (PMID 29802339, 2018). "The prevalence of insulin resistance in childhood is not well known yet7 and its diagnosis is very difficult due to the lack of a single methodcapable of estimating the level of individual sensitivity to insulin." (PMID 30365811, 2018). "We asked if the insulin/Snail1 axis is impaired in obesity, owing to insulin resistance." (PMID 30013137, 2018). "We have previously reported that recuperated offspring show molecular defects in expression of key components of the insulin signalling pathway in peripheral tissues, thus this may contribute to the insulin resistance shown in the clamp." (PMID 30043179, 2018). "The development of this insulin resistance in the liver may result from the lower control of fructose metabolism by insulin or the adipokine leptin." (PMID 29323186, 2018). "In addition, GC opposes the effects of insulin leading to GC-induced insulin resistance which diminishes the suppression of glucose production and reduces peripheral glucose uptake." (PMID 30212527, 2018). "In people with insulin resistance, the cells fail to produce a normal response to insulin." (PMID 29793507, 2018). "Notably, there are reports showing that while glucocorticoid treatment induces insulin resistance in primary adipocytes isolated from human omental white adipose tissue, it actually enhances insulin action in human primary subcutaneous adipocytes." (PMID 30310815, 2018). "A number of previous studies established that the ethanolic extract from A. dracunculus termed PMI5011 enhances insulin signaling in skeletal muscle and improves insulin sensitivity on a preexisting background of insulin resistance in vitro and in vivo in male mice." (PMID 30208938, 2018). "In particular, in our young patients with eGFR > 1 SD, systolic blood pressure, glucose, and insulin levels in response to OGTT and insulin resistance were higher, whereas insulin sensitivity was lower compared to other subgroups, suggesting a glucose dysregulation mainly after OGTT." (PMID 29505614, 2018). "However, we did observe reduced insulin signaling in obese during 12 h of fasting and this resembles insulin resistance in T2D participants." (PMID 30183740, 2018). "Similarly, 14-day high-fat high-sucrose diet (HFHSD) feeding, which is sufficient to induce maximal adipose tissue insulin resistance, impaired insulin-stimulated 2DOG uptake into adipose tissue explants." (PMID 29599292, 2018).
Insulin resistance (continued). "One previous cross-sectional study in adults found that insulin sensitivity mediated the relationship between weight status, measured by BMI, and brain activation during a working memory task, which is in contrast to our findings on insulin resistance." (PMID 29912925, 2018). "As the precursor to the onset of overt disease, insulin resistance is characterized by a reduced cellular response to insulin and this requires the body to compensate by increasing insulin secretion to obtain the biological effects normally achieved with a lower amount of insulin." (PMID 29601521, 2018). "Insulin resistance recognizes multiple abnormalities that may occur in the insulin signaling pathway." (PMID 29619007, 2018). "The lowering of blood glucose and the simultaneous decrease in insulin secretion might explain the alleviation of insulin resistance." (PMID 29541641, 2018). "Long-term improvements in insulin action due to CPAP would support the hypothesis that OSA leads to or exacerbates insulin resistance and undermine the hypothesis that insulin resistance itself was leading to OSA." (PMID 30127766, 2018). "Furthermore, in vitro induction of insulin resistance by chronic exposure of 3T3‐L1 adipocytes to high concentrations of glucose and insulin also increased NECC2 content." (PMID 30160359, 2018). "Notably, overexpression of ATG14 alone improved insulin sensitivity in vivo, suggesting a role of autophagy in insulin resistance." (PMID 29540751, 2018). "Although some phthalates and PFASs have been linked to impaired insulin sensitivity in humans, some studies have failed to reproduce the link between PFASs and insulin resistance." (PMID 29744538, 2018). "Insulin resistance is classically defined as the reduced ability of insulin to stimulate glucose disappearance in peripheral tissues as well as inhibit hepatic glucose production and adipose tissue lipolysis, which corresponds to the main metabolic actions of insulin." (PMID 29971102, 2018). "Notably, plasma insulin, C-peptide concentrations and derived insulin resistance status (HOMA-IR) were negatively correlated with CVFL." (PMID 30347828, 2018). "Different studies regarding adiponectin role on glucose homeostasis showed that this adipocytokine increases the insulin sensitivity in peripheral tissues; on the other hand, decreased plasma adiponectin levels in obesity and type 2 diabetes contribute to insulin resistance." (PMID 29623046, 2018). "Furthermore, waist circumference and BMI correlated positively with insulin resistance, TGs, and fasting insulin and inversely with insulin sensitivity." (PMID 29611319, 2018). "Ca2+ alterations may impair insulin signal transduction, thereby contributing to peripheral insulin resistance." (PMID 29449808, 2018). "Conversely, GHT proves to be more frequently associated with a subtle form of insulin resistance that can be assumed to be the mechanism by which basal glucose does not significantly change after GHT despite the increase in insulin levels." (PMID 29942285, 2018). "With regards to the mechanism underlying the effect of serum UA on insulin resistance and insulin secretion, there is no definite explanation despite numerous animal and clinical studies." (PMID 29568712, 2018). "Management of insulin resistance usually requires an increase in insulin dose requirement." (PMID 29338714, 2018). "Given its association with endothelial function and blood flow, the role of insulin and insulin resistance requires further exploration in relation to epicatechin, particularly as it has been shown to predict the overall cognitive performance changes following CF supplementation." (PMID 30060538, 2018). "The experimental studies showed that the mechanisms of fetal programming on insulin resistance and insulin secretion may be sex-specific, which may be related to the interpretation of sex differences in glucose tolerance." (PMID 29857478, 2018).
Insulin resistance (continued). "Omentin is deemed to play a role in insulin resistance by enhancing subcutaneous glucose transport, and available research indicates a positive correlation between plasma adiponectin and omentin in regulating insulin sensitivity and glucose and lipid profiles." (PMID 30151379, 2018). "In contrast, insulin concentrations were significantly lower in the HFHS-CD group than in the HFHS-HFHS group, but were not different between the CD-CD and the CD-HFHS groups, suggesting that a slight increase in insulin compensated for insulin resistance in the HFHS-HFHS group." (PMID 29769570, 2018). "Additionally, Pik3c3 mutants were less resistant to insulin as homeostasis model of insulin resistance (HOMA-IR) were significantly reduced." (PMID 29695642, 2018). "Berberine treatment may improve insulin resistance, promote insulin secretion, inhibit gluconeogenesis in liver, stimulate glycolysis in peripheral tissue cells, modulate gut microbiota, reduce intestinal absorption of glucose, and perturb lipid metabolism." (PMID 29616225, 2018). "In addition, hydrogen peroxide impairs insulin signaling and inhibits glucose transport, two cardinal features of insulin resistance." (PMID 29791650, 2018). "In our study, we found that decreased CYP-17 was correlated with a low glucose/insulin ratio, which might reflect the insulin resistance detected in our animal model." (PMID 29490689, 2018). "While the inflammatory profile of pregnancy is dynamic, disruptions in inflammatory cytokine profiles and macrophage infiltration of insulin sensitive tissues (such as white adipose tissue) can contribute to worsening insulin resistance thereby contributing to the development of GDM." (PMID 30400566, 2018). "While insulin may have an anabolic effect on bone resulting in higher BMD, insulin resistance has been associated with smaller bone size at the tibia and distal radius." (PMID 29946974, 2018). "This transitory increase in insulin resistance may be caused by EIMD, which may impair insulin signal transduction via inflammatory processes and decrease glucose transporter proteins." (PMID 30131705, 2018). "In addition, we found that insulin resistance measured by GU was only partially similar across all insulin-sensitive tissues studied, skeletal muscle, adipose tissue and liver and was affected by obesity, aging and gender." (PMID 29535167, 2018). "Markers of insulin resistance (IRm), such as high serum levels of insulin, insulin-like growth factor I (IGF-I), glucose, and the metabolic syndrome are associated with an increased risk of sporadic BC and may also affect BC prognosis." (PMID 30181513, 2018). "Expectedly, plasma leptin levels correlated with anthropometric parameters in all participants and individual groups as well as with insulin levels, homeostasis model assessment of insulin resistance (HOMA-IR) and beta cell function (HOMA-β) in the total cohort." (PMID 29795184, 2018). "In addition, expression of HA in the ECM is associated with diet-induced insulin resistance and was reversed upon treatment with the drug pegylated recombinant human hyaluronidase (PEGPH20), which improves insulin sensitivity in muscle tissue." (PMID 30567565, 2018). "Obesity is known to mediate esophageal carcinogenesis through different mechanisms including insulin-resistance leading to hyperinsulinemia, which may mediate cancer progression via the insulin/insulin-like growth factor axis." (PMID 29662006, 2018). "The development of obesity and insulin resistance in adult mice was shown to occur concomitantly with increased cardiac size and impaired cardiac insulin signalling due to an increase in Ptpn1-IRβ, a decrease in IRS1 phosphorylation, and reduced PKB-IRS1associated activity." (PMID 29484207, 2018). "In insulin resistance, although insulin is secreted, its effect decreases." (PMID 29942356, 2018). "Insulin resistance in peripheral tissues decreases insulin-stimulated glucose uptake." (PMID 29707577, 2018).